CTLA4 (cytotoxic T-lymphocyte associated protein 4)
Diseases named in the same sentence as CTLA4 in open-access papers (continued):
Sharing a sentence is not in itself a finding about the gene and the disease.
ovarian carcinoma (continued). "Notably, our study found that crucial immune repressive receptors—which have gained significant attention in ovarian cancer research, such as TIM3, CSF1R, CTLA4, PD1, and LAG3 as well as inhibitory enzymes such as IDO1—were closely related to ALOX5AP expression." (PMID 34094977, 2021). "Thus, targeting CTLA-4 within the intact tumor microenvironment of tumor fragments enriches tumor-reactive TILs and may improve clinical outcome of TIL-based ACT in ovarian cancer." (PMID 32127601, 2020). "Furthermore, CTLA-4 antibody blockade has been shown to reduce MDSC suppressive potency in vitro, and in vivo in a murine ovarian carcinoma model, and this effect was achieved both indirectly through inhibiting T cell-MDSC interaction and directly through binding to CTLA-4 expressed on MDSC." (PMID 26196012, 2014). "Furthermore, the survival analyses of patients with ovarian cancer clearly indicated that the expression levels of PD-1/PD-L1/CTLA-4 had no significant influence on overall survival (OS), and PD-1/CTLA-4 had significant influence on disease-free survival (DFS) while PD-L1 had nonsignificant." (PMID 35991556, 2022). "Alternatively, Quezada and colleagues show that checkpoint anti-CTLA-4 blockade in combination with vaccine therapy could also be effective at altering the balance without eliminating Tregs, suggesting a potential usage for the recently approved anti-human CTLA-4 antibody in ovarian cancer." (PMID 24244610, 2013). "Furthermore, gene therapy in combination with immunotherapy, e.g., targeting CTLA-4 and PD-1, or with the emerging therapeutic angiogenesis inhibitors, may result in increased effectiveness, especially for ovarian cancer in advanced stages, where still no effective therapies exist." (PMID 35805007, 2022). "Currently, although numerous molecular subtyping has been developed in ovarian cancer, such as IFNG, CD30, CXCL13, PRF1 GBP1, and ETV7 CTLA-4, they provided limited prognostic information or are not validated in the clinical samples." (PMID 36157232, 2022). "The increase in local IFNγ in response to the combination of anti-CTLA-4 and PARPis was sufficient to inhibit tumor growth, but this combination had no such effect on BRCA1-sufficient ovarian cancer cells that were inoculated into the mice." (PMID 30487462, 2018). "Thus, the addition of anti-CTLA-4 antibody during the initial TIL culture increases the proportion of CD8+ T cells in ovarian cancer TILs and leads to an increased amount of CD8+ T cells after the rapid expansion without additional anti-CTLA-4 antibody during the rapid expansion." (PMID 32127601, 2020).
gastric cancer (133 papers, 2012 to 2026). A primary or metastatic malignant neoplasm involving the stomach. "Malignancies, particularly lymphomas and gastric cancer, have been reported in approximately 12–13% of individuals with CTLA-4 haploinsufficiency, but associations with chronic myeloid leukemia (CML) are very rarely described." (PMID 41582224, 2026). "Immune checkpoint blockade therapy targeting programmed cell death protein-1 (PD-1), programmed death-ligand 1 (PD-L1), and cytotoxic T-lymphocyte-associated protein 4 (CTLA-4) has emerged as a promising treatment option for gastric cancer." (PMID 41225987, 2025). "Blocking the programmed cell death (PD)-1 protein, its ligand (PD-L1), and cytotoxic T-lymphocyte-associated protein 4 (CTLA-4) was reported to achieve durable responses in advanced gastric cancer patients." (PMID 37048719, 2023). "The prognostic risk score model was found to identify patients with gastric cancer who are suitable for anti-CTLA4 antibody immunotherapy sucessfully, and thereby also indicated that fatty acid metabolism is crucial for shaping individual TME characteristics." (PMID 36591293, 2022). "A cytotoxic T-lymphocyte-associated protein 4 (CTLA4) inhibitor, ipilimumab, has been used to treat patients with advanced gastric cancer in a phase II clinical study (NCT01585987)." (PMID 36741400, 2022). "CTLA-4 polymorphisms have a tight relationship with digestive system malignancies including gastric cancer, it related to predisposition to GC." (PMID 34281542, 2021). "At present, immunotherapy has always been a potential part of comprehensive therapy for gastric cancer through blocking immune checkpoints, such as cytotoxic T-lymphocyte-associated antigen 4 (CTLA-4), programmed cell death-1 (PD-1), and its ligand (PD-L1)." (PMID 33015704, 2020). "For example, genetically predisposed CTLA4 insufficiency in humans has been associated with gastric cancer (GC) development." (PMID 31358815, 2019). "Currently, available ICIs for gastric cancer include inhibitors of PD-1 and its ligand (PD-L1), which block the interaction that typically suppresses T-cell activity, as well as inhibitors targeting cytotoxic T-lymphocyte-associated antigen 4 (CTLA-4)." (PMID 40075656, 2025). "A seminal study in 2018 revealed that Th2, and notably not Th1 or Th17, immune responses are responsible for mediating the link between gastritis and gastric cancer; specifically, CTLA4 deficiency induces Th2-dependent immune dysregulation that results in the development of gastric cancer." (PMID 38339273, 2024). "In addition, it has been shown that tumor-infiltrating FoxP3highCD45RA− effector Tregs, which express PD-1, are highly activated, express high levels of CTLA-4 and are associated with hyper progressive disease in patients with advanced gastric cancer." (PMID 31921188, 2019). "Both patients who developed EBV-associated gastric cancer had received abatacept, a CTLA-4-Ig-fusion-protein, which is expected to improve especially the gastrointestinal symptoms in adult autoimmune enteropathy but could raise EBV serum levels." (PMID 30250467, 2018). "Cadonilimab, a PD-1 and CTLA-4 bispecific antibody, has shown encouraging efficacy and safety in the first-line treatment of advanced gastric cancer." (PMID 40040691, 2025). "LAG-3, an emerging immune checkpoint molecule, is often co-expressed with PD-1 in infiltrating lymphocytes of gastric cancer, and its high expression is frequently accompanied by upregulation of PD-L1 and CTLA-4, as well as higher TMB." (PMID 41228276, 2025). "Cadonilimab, the first approved PD-1/CTLA-4 blocker, has been authorized for the treatment of cervical and gastric cancers in China." (PMID 40248696, 2025). "By examining the current therapeutic landscape for MSI-H gastric cancer, this study explores the potential of combining PD-1/CTLA-4 dual-immunity with anti-vascular therapy as salvage treatment for this gastric cancer subtype." (PMID 40040691, 2025).
gastric cancer (continued). "We used the IPS score and TIDE score of anti-PD-1 and anti-CTLA-4 to forecast the effectiveness of immunotherapy in gastric cancer patients categorized as high or low RCDRI group." (PMID 41000398, 2025). "Cadonilimab represents the inaugural anti-PD-1/CTLA-4 bispecific antibody to be employed in the treatment of advanced gastric cancer." (PMID 39996912, 2025). "Immunotherapy research in gastric cancer has focused on typical immune checkpoint pathways such as PD-1/PD-L1, CTLA-4, and LAG-3." (PMID 41228276, 2025). "Experiments in vitro and in vivo demonstrated that METTL1 enhances gastric cancer cell activity by suppressing T cell proliferation and upregulating CTLA4 and PDCD1." (PMID 38693422, 2024). "In contrast, persons with low HIGD1B had higher TMB values and MSI-H ratios in gastric cancer and had better efficacy for CTLA-4 immunotherapy." (PMID 39108265, 2024). "In the cohort of 131 patients with CTLA-4 insufficiency, 13% of the affected CTLA4 variant carriers had a malignant cell growth, most frequently EBV-associated lymphomas and gastric cancer." (PMID 37780100, 2023). "Haplotype analysis revealed that the TACG haplotype for the CTLA-4 variants (−1722T, −1661A, −318C, +49G) was significantly associated with an increased risk of CRC and gastric cancer." (PMID 37107632, 2023). "This interaction between CTLA4 on Tregs and tumor cell ligands inhibits the activation of effector T cells and promotes immune evasion in gastric cancer." (PMID 37999824, 2023). "Concurrently, the CTLA4– PD1+, CTLA4+ PD1–, and CTLA4+ PD1+ subgroups exhibited a notable advantage in immunotherapy for low-risk gastric cancer." (PMID 37711621, 2023). "In this study, the gastric cancer patients with high expression of CTLA4 and ENTPD2 had a better survival prognosis, with high expression of CLDN6, EMB, GPR15, VWF and AKR1B1 suggesting poor prognosis, which was consistent with previous studies." (PMID 37066015, 2023). "Immunotherapy via blocking the PD1/PDL1 axis or via blocking CTLA4 signaling has become standard of care in several cancer indications and has yielded promising results in gastric cancer as well." (PMID 36550535, 2022). "CTLA-4 inhibitors tremelimumab and ipilimumab have been evaluated in clinical trials of advanced gastric cancer." (PMID 35844558, 2022). "Among five hub genes, we focused on CPVL because it showed the highest degree of correlation with immune cell infiltration and immune checkpoints PD-1/PD-L1 and CTLA-4 in gastric cancer." (PMID 35754804, 2022). "CTLA-4 inhibitors and PD-1/PD-L1 have been used in the treatment of advanced gastric cancer, improving the prognosis of patients to a certain extent." (PMID 35528539, 2022). "ICIs are an important aspect of immunotherapy, including anti-PD1 and anti-CTLA4 antibodies, which have continuously improved the survival of gastric cancer patients and progressed from back-line to front-line status in clinical practice." (PMID 36092932, 2022). "Results of major clinical trials of PD-1/PD-L1 and CTLA-4 immune checkpoint inhibitors in the treatment of gastric cancer." (PMID 36225938, 2022). "Ipilimumab, as an anti-CTLA4 antibody, when combined with nivolumab, has been shown to be highly effective for dMMR gastric cancer (ORR 70, 95% confidence interval 35, 93 versus 57, 95% confidence interval 18, 90)." (PMID 36042469, 2022). "Meanwhile, a positive relationship between CTLA-4 and PD-L1 expression was noted in gastric cancer (P < 0.05)." (PMID 34421887, 2021). "Increasingly immunotherapy trials continue to examine the benefits of PD1/PD-L1 and CTLA4 blockade and will likely be incorporated into the treatment pathways of advanced gastric cancer." (PMID 32959118, 2021). "IHC was performed to explore the expression of PD-L1 and CTLA-4 in gastric cancer and then analyzed their correlations with GARP expression." (PMID 34421887, 2021).
gastric cancer (continued). "Paradoxically, patients who display a “natural” inhibition of CTLA-4, and especially CTLA-4-insufficient patients and DEF6-deficient patients, have an increased risk for malignancies, frequently EBV-associated lymphomas and gastric cancers." (PMID 33996698, 2021). "Recently cancer prevalence of 12.9% was documented among 184 CTLA-4 deficient patients, highlighting the increased risk for malignant transformation, especially EBV+ lymphomas and gastric cancers." (PMID 31799221, 2019). "While anti-CTLA4 showed only slight activity in gastric cancer, and PD-1 and PD-L1 inhibitors showed promising results and will probably take place in gastric cancer management in the near future." (PMID 30027089, 2018). "As detailed before, immune checkpoint blockade with antibodies targeting CTLA-4, PD-1, and PD-L1 has revealed clinical activity in gastric cancer." (PMID 30027089, 2018). "By blocking the interaction of CD8+ T cell-related receptors (CTLA-4 and PD-1) and ligands (PD-L2 and PD-L1), anti-tumor immunity is enhanced in patients with advanced solid tumor, including gastric cancer." (PMID 28915679, 2017). "We also evaluated the correlation between CD163 expression with two key immune checkpoints PD-L1 and CTLA4 in gastric cancer cell lines." (PMID 29152078, 2017). "Although there was no statistical significance, better prognoses were also noted for gastric cancer patients with CTLA-4 expression in the tumors." (PMID 26918337, 2016). "Cadonilimab is the world’s first PD-1/CTLA-4 bispecific antibody tumor immunotherapy drug developed independently in China and provides critical evidence supporting updates to clinical practice guidelines for gastric cancer." (PMID 41164188, 2025). "PD-1 and CTLA4 are two classic immunotherapy targets for gastric cancer at present." (PMID 39028440, 2024). "Moreover, low-risk gastric cancer patients with CTLA4- PD1+, CTLA4+ PD1-, and CTLA4+ PD1+ subtypes also exhibited improved response to immunotherapy." (PMID 37711621, 2023). "Correlation of IFN-γ in tumors with CTLA-4 lymphocytes in gastric cancer." (PMID 36979688, 2023). "In gastric cancer, significant benefits were observed after inhibiting PD-L1 and CTLA4." (PMID 35778697, 2022). "However, the efficacy of CTLA-4 inhibitor as a monotherapy in advanced gastric cancer remains to be further investigated." (PMID 35844558, 2022). "In addition, GARP expression had positive relationships with CTLA-4 and PD-L1 expression in gastric cancer." (PMID 34421887, 2021). "Some research also indicates CTLA4 may have influence on gastric cancer germination and progression." (PMID 30400837, 2018). "Interestingly, this observation is paralleled by our results in CTLA-4-insufficient patients, showing predominantly lymphoma and gastric cancer." (PMID 30250467, 2018). "High mRNA expression of PD-1, CTLA4 and Dies1/VISTA and distinctive PD-1/PD-L1 co-expression patterns (PD-1high/PD-L1low, PD-1high/PDL1high) were associated with MSS/EBV+ molecular subtype and gastric cancer with lymphoid stroma (GCLS) morphological features." (PMID 30018250, 2018). "Interestingly, 3 of the 24 (12.5%) cases with CTLA4 haploinsufficiency reported developed gastric cancer and 2 of 3 patients presented with multifocal adenocarcinomas associated with atrophic gastritis and intestinal metaplasia, similarly to our patient." (PMID 28720148, 2017). "Blocking antibody for immune checkpoints such as programmed death-ligand 1 (PD-L1), programmed cell death 1 (PDCD1) and cytotoxtic T-lymphocyte antigen 4 (CTLA4), have been used to treat several tumors including melanoma, renal cell carcinoma, lung cancer and gastric cancer." (PMID 29152078, 2017). "In gastric cancer, CTLA-4 was expressed in the cytoplasm of tumor cells." (PMID 26918337, 2016).
gastric cancer (continued). "A phase II clinical trial investigated the CTLA4 inhibitor tremelimumab for patients with gastric cancer (GC) and EAC; a small cohort of patients received a significantly long-lasting benefit and acquired clinical benefit with mild drug-related toxicity." (PMID 36119033, 2022). "IPS-PD-1/PD-L1/PD-L2_pos and IPS-CTLA-4_pos was higher in low-risk group patients than in high-risk group patients, indicating that low-NRG_risk gastric cancer patients might have higher tumor immunogenicity and benefit from anti- PD-1/PD-L1/PD-L2 and anti- CTLA-4 blocker immunotherapy." (PMID 36092932, 2022). "In particular Non-Asian gastric cancer seemed to be associated with enrichment of tumor infiltrating T-cells as well as T-cell gene expression signatures, including CTLA-4 signaling, while Asian gastric cancers had a significantly higher numbers of cells positive for neutrophil markers." (PMID 30205505, 2018). "A number of T cell co-inhibitory molecules CTLA4, ICOS, CD274, PDCD1, and IDO were markedly downregulated by NPRL2 treatment which was in agreement with the data found in bioinformatics analysis in stomach cancer patients' samples." (PMID 39932765, 2025). "We conducted mIHC staining analysis on sections of human gastric cancer TMAs to assess NKAIN1 protein expression and visualize tumor-infiltrating immune cells (TIICs) and immune checkpoints (PD-1, PD-L1 and CTLA-4)." (PMID 41350575, 2025). "This overexpression also enhances the expression of immune checkpoint proteins, CTLA4 and PDCD1, ultimately inhibiting immunotherapy targeting gastric cancer cells." (PMID 38693422, 2024). "Previous research has demonstrated that CTLA4 and PDCD1 are biomarkers with high expression levels in gastric cancer tissues." (PMID 38693422, 2024). "We further accessed the expression of B cells, CD4+ T cells, CD8+ T cells, macrophages, neutrophils, and immune checkpoints (CTLA4, LAG3, PD-1, and PD-L1) in gastric cancer tissues using IHC and mIHC staining and multispectral image analysis." (PMID 38887558, 2024). "AUC values were higher than 0.75 in two anti-PD-1 treatments and one anti-PD-1/anti-CTLA-4, suggesting that IRS is relevant for predicting sensitivity to immunotherapy in patients with gastric cancer." (PMID 37120631, 2023). "High THSD7A expression suppressed the sensitivity of patients with gastric cancer to drugs, such as 5-fluorouracil, bleomycin, and cisplatin, and upregulated immune checkpoints, such as HAVCR2, PDCD1LG2, TIGIT, and CTLA4." (PMID 37905960, 2023). "The immune checkpoint analysis indicated that gastric cancer patients with upregulated GGT5 expression showed a higher TIDE score and expression of CD274, CTLA4, HAVCR2, LAG3, PDCD1, PDCD1LG2, and TIGIT than patients in the GGT5-low expression group." (PMID 35368661, 2022). "Other inhibitors or agonists of immune checkpoint molecules, including the inhibitors of CTLA4, LAG3, Tim3, and TIGIT, as well as the agonists of OX40, are currently in clinical trials in the treatment of gastric cancer." (PMID 36042469, 2022). "Lpilimumab, a monoclonal antibody, activates the immune system by targeting CTLA4 and has been approved by the FDA for the treatment of advanced gastric cancer." (PMID 35627105, 2022). "At present, immunotherapy for gastric cancer mainly includes anti-CTLA-4, anti-PD-1/PD-L1, or the combination of anti-CTLA-4 and anti-PD-1 antibodies." (PMID 35083327, 2022). "In this study, we conducted immunohistochemical (IHC) studies of CTLA-4, PD-1, PD-L1, and CD8 using 464 gastric cancer tissue microarrays and evaluated the expression of molecular markers related to immune checkpoint inhibition." (PMID 27741514, 2016). "The research results indicated that there exists a significant positive correlation between DLX2 and CTLA4, PDCD1, HAVCR2 and TIGIT, which may contribute to the gastric cancer cells’ ability to evade immune system attacks." (PMID 41244921, 2025).